BID (BH3 interacting domain death agonist)
Diseases named in the same sentence as BID in open-access papers (continued):
Sharing a sentence is not in itself a finding about the gene and the disease.
cancer (continued). "The level of BID is critical for the viability of numerous types of cancer cells since its silencing makes them resistant to apoptosis induced by death receptor ligands, whereas overexpression sensitizes certain types of cancer cells to TRAIL or etoposide." (PMID 25760094, 2015). "The main finding of this work is that direct delivery of recombinant BID fused with the TAT cell penetrating peptide allows for controlled sensitization of cancer cells to apoptosis induced by TRAIL and CPT." (PMID 25326334, 2014). "TMEM106A induces cancer cell apoptosis through caspase-2/BID activation and the mitochondrial pathway." (PMID 24975047, 2014). "Estimated levels of endogenous BID in examined cancer cell lines varied from about 10 fg/cell for LNCaP to about 35 fg/cell for A549 cells." (PMID 25326334, 2014). "Most authors reported activation of apoptosis in cancer cells under the effect of Helicobacter pylori, with activation of its mitochondrial pathway and increased expression of BID and Bax, or antiapoptotic Bcl-2." (PMID 24741635, 2014). "It is worth noting that BID was widely expressed in the 22 cancer cell lines." (PMID 38676703, 2024). "Thus, one suggested functional strategy for cancer therapy is inducing the overexpression of BID using pcDNA or adenovirus vectors; however, achieving precise control over the cellular level of BID is a difficult task." (PMID 34575464, 2021). "However, in ‘type II cells’, which includes most cancer cells, the extrinsic pathway relies on cleavage of BID by caspase 8 to form truncated BID (tBID)." (PMID 35008216, 2021). "Studies have shown BID and Bcl2 as molecules acting upstream and downstream of MuD, respectively, suggesting that MuD may perform a novel role in the cancer apoptotic pathway." (PMID 31616474, 2019). "Efforts to exploit aneuploidy tolerance mechanisms and the BCL9L/caspase-2/BID axis may limit cancer diversity and evolution." (PMID 28073006, 2017). "In addition to suggesting the potential therapeutic use of TAT-BID in combination with DOX, this study presents some observations and raises various questions concerning the role of BID in the apoptosis induced by DOX in different types of cancer cells." (PMID 25760094, 2015). "Low cellular level of BID is critical for viability of numerous cancer cells." (PMID 25326334, 2014). "The aim of this work was to examine whether a fusion of BID with TAT cell penetrating peptide (TAT-BID) may be used for controlled sensitization of cancer cells to anticancer agents acting through death receptors (TRAIL) or DNA damage (camptothecin)." (PMID 25326334, 2014). "Hence, assessment of caspase-2 and BID expression levels may help to identify cancers that respond to these therapies." (PMID 39475598, 2024). "Our findings also demonstrate that the pro-apoptotic potential of BID is negatively regulated by N-terminal cysteines, indicating that these cysteines could be targeted by covalent inhibitors for the induction of apoptosis and potential cancer therapeutics." (PMID 39472556, 2024). "Similarly, research by Jelinek and Wang also found that knocking out the BID gene or using BID inhibitors could protect cells (including normal cells and a variety of cancer cells) from RSL3- or Quercetin-induced cell death by preventing mitochondrial damage." (PMID 35155251, 2022). "Combined with the increased sensitivity of the high-risk group to ferroptosis caused by the high expression of BID and TAZ, we speculated that the overexpression of CD44 may play a role in antagonizing TAZ and BID, thereby making cancer cells resistant to lipid peroxidation-mediated ferroptosis." (PMID 35155251, 2022). "Understanding aneuploidy tolerance mechanisms more widely, and the BCL9L/caspase-2/BID axis specifically, may unravel potential vulnerabilities in aneuploid cancers, which could be exploited to limit intercellular heterogeneity, a substrate for selection and tumor evolution." (PMID 28073006, 2017).
cancer (continued). "One notable example is a 322 bp deletion within an enhancer upstream of BID, a pro-apoptotic BCL-2 family member involved in cancer progression and immune regulation." (PMID 41256123, 2025). "We treated 6 cancer cell lines with RSL3 alone or in combination with inhibitors of ferroptosis (Ferrostatin-1), caspases (zVADfmk), necroptosis (Necrostatin-1), BID (BI-6C9), or STING (H-151)." (PMID 40652037, 2025). "Apoptosis-mediated death of cancer cells is achieved by the upregulation of pro-apoptotic genes, such as BAX, BID, and BAK, and the downregulation of anti-apoptotic genes, such as BCL-2 and BCL-XL respectively." (PMID 40756996, 2025). "K-means clustering of >600 000 cancer cells and cell level intensities of APAF1, procaspase-9, procaspase-3, XIAP, SMAC, BAX, BAK, BCL2, BCL-XL, MCL-1, procaspase-8, BID, FADD, FLIP, RIP3 and CIAP1 identified distinct cell cluster profiles." (PMID 39886119, 2024). "Apoptosis (e.g., BID, CASP6, etc.)and aminoacyl-tRNA biosynthesis (e.g., CARS2 and AARS2) were predominant in the D4 (HGIN stage), suggesting cancer malignancy." (PMID 36991000, 2023). "Autophagy-related genes BID, EIF4EBP1, VMP1, SPHK1, and CX3CL1 also play essential roles in other cancers." (PMID 33224313, 2020). "Tissue microarray analysis (TMA) was also performed for three randomly picked common cancer genes (SPP1, BID and CLU) to determine if mRNA changes were correlated with changes in protein expression in cancer patients." (PMID 17989776, 2007). "Elevated ROS levels not only directly impair tumor cell viability but also sensitize cancer cells to apoptosis by activating caspase-8 and mitochondrial translocation of truncated BH3 Interacting Domain Death Agonist (tBID), especially under nutrient-deprived conditions." (PMID 41163402, 2025). "In this study, we developed alkynyl-functionalized ITC-derived chemical probes for globally profiling the target proteins of ITCs, identified BID as a novel target of BITC, PEITC, and SFN in human cancer cells, and revealed the function of covalent binding of BID with PEITC in mediating apoptosis." (PMID 39472556, 2024). "The results of immunohistochemical staining of tumor samples collected from the hospital also demonstrated that BID protein was highly expressed in the cytoplasm of ccRCC tissues, while low or no expression in normal renal tissues adjacent to cancer." (PMID 38767695, 2024). "Although BH3 mimetics have been developed as potential apoptosis-inducing and cancer therapeutic agents, small molecules directly targeting BID have not been reported yet." (PMID 39472556, 2024). "When BID is expressed and activated by BSB, Beclin 1 ends up being degraded and autophagy collapses; when BID is not available, Beclin 1 persists and the continuous autophagic flux probably helps cancer cells survive." (PMID 31767857, 2019).
cancer (continued). "Similarly, we found 11 hub coding genes, including apoptosis-regulatory gene (BID) and DNA double-strand break repair gene (RAD51AP1) etc., which are closely related to cancer development." (PMID 27966444, 2016). "Sensitization of cells to anticancer agents by BID overexpression from adenovirus or pcDNA vectors is a proposed strategy for cancer therapy; however it does not provide any stringent control of cellular level of BID." (PMID 25326334, 2014). "BID is also a pro-apoptotic member of the B-cell lymphoma-2 (Bcl-2) group of proteins, which have a high expression level in RCC and may participate in the progression of cancer." (PMID 31739630, 2019). "In summary, our results indicate that recombinant BID fused with TAT peptide may be delivered to cells in controlled manner so that it is not toxic but it sensitizes cancer cells to apoptosis." (PMID 25326334, 2014). "Therefore, sensitization of cancer cells to apoptosis based on substitution of BID by its unphosphorylable analogue does not seem to be better strategy at least for cancer lines studied in this work." (PMID 25326334, 2014). "In the present work, we observed that pro-apoptotic proteins, Bad, Bax, and BID, are highly expressed in AGS and HT-29 cancer cells in response to 5-ISA- and 3,5-diISA-fortified lettuce vs. negative control (except BID after 3,5-diISA in AGS)." (PMID 37373017, 2023). "Therefore, as the level of endogenous BID, functioning of TRAIL-induced signaling, and activity of CK2 differ in particular cancer cells, some cells may be expected not to respond on elevation of cellular concentration of BID whereas other ones may be sensitized by BID." (PMID 25326334, 2014).
tumor (72 papers, 2009 to 2025). "We also used the TISCH database to probe BID expression in single-cell immune populations associated with tumor microenvironment (TME)." (PMID 39023752, 2024). "The depletion of hepatocyte-specific BID can reduce tumor development by inhibiting inflammation-associated compensatory proliferation." (PMID 38767695, 2024). "The presence of pro-apoptotic BID can also determine tumor cell susceptibility to extrinsic apoptotic stimuli, suggesting that both quantity and ratio of BID splice variants can strongly influence AML development and chemoresistance." (PMID 27613060, 2016). "However, VHL mutation, SETD2 mutation and BAP1 mutation had mutational differences of up to 10% between the two groups, suggesting that differential expression of BID mediates differential tumor mutational signatures." (PMID 38767695, 2024). "This indicates BID may be a risk gene of ccRCC and participate in tumor progression." (PMID 38767695, 2024). "Among pro-apoptotic BCL-2 family genes, BID expression was lower in tumor cells, and in the IAP family, XIAP expression tended to be higher in tumors relative to non-tumor cells." (PMID 39122703, 2024). "Subsequently, we will explore the effects of BID reduction on tumor cells by functional experiments in CAKI and ACHN cell lines, where we reduced BID expression by small interfering RNA (siRNA)." (PMID 39023752, 2024). "Consistent with our expected result, the differential expression of BID was further verified in tumor tissues and normal renal tissues (P < 0.001)." (PMID 38767695, 2024). "We used transcriptome information of 539 ccRCC tumor samples and 72 matched paracancerous samples to explore the differential expression of BID." (PMID 38767695, 2024). "The screened BID gene was confirmed to be involved in enhancing tumor cell migration through in vitro experiments." (PMID 39023752, 2024). "Meanwhile, the pro-apoptotic gene BID can activate the growth-orientated pathways by promoting both cell proliferation and compensatory stimulus of tumor." (PMID 37760507, 2023). "Our results indicate that, at least in vitro, the sensitivity profiles of tumor cells to both types of drugs are almost identical and suggest BID upregulation as a candidate biomarker to select patients for treatment." (PMID 37443114, 2023). "We have demonstrated that an AURKB/CASP-2 mechanism, regulated by the levels of BID, determines the fate of tumor cells after abrogation of the spindle assembly checkpoint by AURKB or TTK inhibitors." (PMID 37443114, 2023). "The association of BID levels with sensitivity to SAC abrogation was then extensively validated, not only in a total of 32 EGFR-mut clones but also in 21 tumor cell lines of different origins." (PMID 37443114, 2023). "In tumor tissues, the staining intensity of the target genes was strong (BID, HPRT1, SMN1), high (PGAM5), or medium (FADD, KIAA1191)." (PMID 37760507, 2023). "If BID is upregulated, CASP-3 and apoptosis are triggered; but if BID expression is low, the tumor cell survives and enters senescence." (PMID 37443114, 2023). "Meanwhile, the inhibitory role of LINC00472 in tumorigenesis was validated in vivo, and the LINC00472‐mediated miR‐23a‐3p/FOXO3/BID axis was also demonstrated in the nude mouse tumour formation model." (PMID 34363438, 2021). "Through a screening in TCGA-KIRC database, we compared the expression levels of CANX, MAPK1, BIRC5, NAMPT, and BID in normal kidney tissues and renal clear cell tumor tissues, and we found that their expression levels in tumor tissues were upregulated." (PMID 34988121, 2021). "The BmooLAAO-I-induced upregulation of BID and FADDgene expression suggests that the toxin sensitizes leukemic cells to apoptosis,which is an advantage for the treatment of neoplasias, including CML." (PMID 33354202, 2020). "Three of these genes, apoptosis inhibitors BID, BIRC2 and BIRC3 were found in the differential expression analyses, being overexpressed in CTNNB1-mutated tumours." (PMID 31000732, 2019).
tumor (continued). "Bortezomib and TRAIL act in concert to cause accumulation of tBID, the active cleavage product of BID and induce mitochondrial dependent apoptosis of tumor cells." (PMID 25318057, 2014). "Elevated expression of proapoptotic protein BID and damage sensor 53BP1, were also observed in tumor treated tissues, suggesting the activation of apoptosis following 4a treatment." (PMID 22970136, 2012). "When BID expression is low, tumor cells survive and enter senescence." (PMID 41154660, 2025). "Based on our autophagy data we determined whether the role of BID in tumor cell killing was due to canonical signaling from death receptor CD95/FADD though caspase 8 to cleave BID, or through a different mechanism." (PMID 40827882, 2025). "Furthermore, levels of apoptosis related proteins in tumor tissues, including Bim, BID, and BAD, were sharply boosted by sh-TBX21 injection." (PMID 41573646, 2025). "The results of our PCR analysis clearly indicate that BID is up-regulated in tumor tissue." (PMID 39023752, 2024). "Conversely, MCL1 and BID expression were lower in tumor cells compared to non-tumor cells." (PMID 39122703, 2024). "Moreover, the results of transcriptome sequencing of tumor samples also demonstrated that BID was highly expressed in ccRCC tissues and lowly expressed in normal kidney tissues (P < 0.001)." (PMID 38767695, 2024). "While apoptosis-related factors are often associated with tumor suppression, BID’s role in promoting tumor progression was highlighted, potentially through non-apoptotic mechanisms." (PMID 37760507, 2023). "Independently of Chr22q11 status, only tumor cells with high BID levels experienced extensive cell death after SAC abrogation by AURKBi and TTKi, and cut-off values for sensitivity could be established." (PMID 37443114, 2023). "For example, silencing of BID expression renders tumor cells resistant to death ligand-induced apoptosis, thus implying that overexpression of BID may make tumor cells more sensitive to TRAIL." (PMID 37631307, 2023). "The expression level of BID was negatively correlated with tumor purity and the infiltration levels of B cells and has significant positive correlations with CD8+ T cells, dendritic cells, macrophages, and neutrophil, but not with the infiltration levels of CD4+ T cells." (PMID 34868460, 2021). "Determining if BID cleavage is defective in these models would be valuable in determining the true mechanism of tumor suppression by caspase-2 as it would suggest that apoptosis is impaired in these tumors, even though it may be masked in vivo." (PMID 33425918, 2020). "Because cleavage of BID is a well-established contributor to apoptosis, BID proteolysis could be a potential mechanism to explain tumor suppression by caspase-2." (PMID 33425918, 2020). "Although there are few clear examples of an apoptotic defect in caspase-2 deficient tumor models, BID cleavage has not been examined in these models." (PMID 33425918, 2020). "Many of these additional mutated genes are pro-apoptotic, such as CASP8, BID, and SIAH1, suggesting that for relapse tumors to develop, tumor cells might need to acquire extra survival advantages." (PMID 25123191, 2014). "Interestingly, we observed EGF-induced alternative promoter usage of genes that have previously been implicated in tumor progression (e.g., VEGFC, PTK2, IL18 and VAV3) or in cell survival/proliferation (e.g., FBXW7, BID, ABL2)." (PMID 24324612, 2013). "Knock down of BID reduced regorafenib lethality as a single agent, but not that of aramchol; aramchol and regorafenib, regardless of BID expression, interacted to cause more tumor cell death." (PMID 40827882, 2025).